PEBP1 (phosphatidylethanolamine binding protein 1)
Description:
Binds ATP, opioids and phosphatidylethanolamine. Has lower affinity for phosphatidylinositol and phosphatidylcholine. Serine protease inhibitor which inhibits thrombin, neuropsin and chymotrypsin but not trypsin, tissue type plasminogen activator and elastase (By similarity). Inhibits the kinase activity of RAF1 by inhibiting its activation and by dissociating the RAF1/MEK complex and acting as a competitive inhibitor of MEK phosphorylation. HCNP may be involved in the function of the presynaptic cholinergic neurons of the central nervous system. HCNP increases the production of choline acetyltransferase but not acetylcholinesterase. Seems to be mediated by a specific receptor (By similarity).
Synonyms: PEBP-1; RKIP; HCNP; PBP; PEBP; HCNPpp; HEL-210; HEL-S-34; HEL-S-96
Tractability: Small molecule: a structure with a bound ligand is known. Antibody: the Human Protein Atlas places it where antibodies can reach. PROTAC: ubiquitination databases record sites on it; its protein half-life has been measured; a small molecule that binds it is known.
Gene: Protein-coding gene on chromosome 12 (118,136,071 to 118,145,584, forward strand). Ensembl gene ENSG00000089220.
Subcellular location: Cytoplasm
Subcellular location (Human Protein Atlas): Cytosol; Plasma membrane
Pathways (Reactome):
Disease: Paradoxical activation of RAF signaling by kinase inactive BRAF; Signaling by BRAF and RAF1 fusions; Signaling by high-kinase activity BRAF mutants; Signaling by moderate kinase activity BRAF mutants; Signaling downstream of RAS mutants
Signal Transduction: MAP2K and MAPK activation; Negative regulation of MAPK pathway
Gene Ontology:
Molecular function: enzyme binding; protein binding; protein kinase binding; RNA binding; phosphatidylethanolamine binding
Biological process: negative regulation of MAPK cascade
Cellular component: extracellular exosome; nucleus; cytosol; cytoplasm
Genetic constraint (gnomAD): Loss-of-function variants: 10 observed, 15.09 expected, observed/expected ratio (o/e) 0.66, 90% interval 0.41 to 1.12. The upper end of that interval is the gene's LOEUF score, 1.12, which puts it in group 4 of 6, group 1 being the genes least tolerant of losing a copy. Missense variants: 188 observed, 209.21 expected, observed/expected ratio (o/e) 0.9, 90% interval 0.8 to 1.01. Synonymous variants: 100 observed, 89.2 expected, observed/expected ratio (o/e) 1.12, 90% interval 0.95 to 1.32.
Homologues: Orthologues: chimpanzee PEBP1 (100% identical), rabbit PEBP1 (90% identical), mouse Pbp2 (84% identical), rat Pbp2 (84% identical), tropical clawed frog pebp1.2 (63% identical), Drosophila melanogaster CG10298 (52% identical), Caenorhabditis elegans F40A3.3 (50% identical), Drosophila melanogaster CG17919 (49% identical), Drosophila melanogaster a5 (42% identical), Drosophila melanogaster CG7054 (42% identical), Drosophila melanogaster Pebp1 (41% identical), Drosophila melanogaster CG17917 (37% identical), and 1 more. Paralogues in human: MRPL38 (34% identical), PEBP4 (32% identical).
Diseases named in the same sentence as PEBP1 in open-access papers:
PEBP1 is named in the same sentence as 190 diseases in open-access papers, as found by Europe PMC text mining. Sharing a sentence is not in itself a finding about the gene and the disease. The quoted sentences say what the papers report.
breast cancer (81 papers, 2010 to 2026). A primary or metastatic malignant neoplasm involving the breast. "For other subtypes, CS and PEBP1 were significantly associated with breast cancer size (all p < 0.05)." (PMID 35154262, 2021). "GLS2 and PEBP1 were significantly associated with breast cancer grade (all p < 0.05)." (PMID 35154262, 2021). "We used the top five coherent (coherence > 0.6) PEBP1 paths to highlight interactions that are strongly relevant to breast cancer cell metastasis and are highly responsive to treatment with different drugs." (PMID 34885208, 2021). "Remarkably, stratifying breast cancer patients by high RKIP (PEBP1) and low BACH1 expression or vice versa reveals a striking inverse association of RKIP with BACH1 and the motility-related genes in ~60% of patients." (PMID 33973518, 2021). "Overall, these findings suggest that YY1 and PEBP1 CNVs might play a specific role in immune infiltration in breast cancer." (PMID 37894300, 2023). "Similarly, an infiltration for NKT cells has been reported in breast cancer, but this is the first mention of their association with CNVs in genomic regions affecting YY1 and PEBP1 to our knowledge." (PMID 37894300, 2023). "On the other hand, PEBP1 was shown to act as an adverse prognostic factor in brain cancer (meningioma), colorectal cancer, breast cancer, ovarian cancer, and AML and a protective prognostic factor in bladder cancer, lung cancer, adenocarcinoma, and liposarcoma." (PMID 37894300, 2023). "In addition to lung cancer, PEBP1 plays a regulatory role in multiple cancers such as breast cancer, prostate cancer and ovarian cancer." (PMID 37622116, 2023). "However, in the BC cell line (MDA-MB-231), the overexpression of miR-4443 suppresses the expression of PEBP1 and promotes the invasion and metastasis of breast cancer cells." (PMID 36250718, 2022). "Subsequently, we used the ROC plotter tool to analyze the relationship between YY1 (and PEBP1) expression and sensitivity in endocrine therapy, anti-HER2 therapy, or chemosensitivity in breast cancer." (PMID 37894300, 2023). "In breast cancer, miR-4443 inhibits the expression of TIMP metallopeptidase inhibitor 2 (TIMP2) and phosphatidylethanolamine binding protein 1 (PEBP1), thereby promoting the metastasis and invasion of breast cancer." (PMID 36250718, 2022). "In contrast to PEBP1’s role in metastasis, SNAI1 induced breast cancer EMT and metastasis by directly repressing the epithelial markers E-cadherin (CDH1)." (PMID 34885208, 2021).
prostate carcinoma (60 papers, 2007 to 2025). A carcinoma that arises from epithelial cells of the prostate gland. "The loss of RKIP/PEBP1 was initially connected to the development of prostate cancer and later to a few other cancer types." (PMID 30115852, 2018). "While first identified in prostate cancer, the loss of PEBP1 expression is observed in many cancers as they progress." (PMID 29286311, 2017). "In particular, PEBP1 is reported to suppress cell motility and metastasis development and is downregulated in prostate cancer." (PMID 39531326, 2024). "We first used the cRegulome to identify transcription factors and microRNAs that target PEBP1 in prostate cancer study (PRAD)." (PMID 30867986, 2019). "In this study, we used the weighted-gene co-expression network analysis (WGCNA) to find the epithelial to mesenchymal transition (EMT) and autophagy gene products that potentially interact with PEBP1 during the development of prostate cancer." (PMID 30867986, 2019). "Finally, we found several upstream regulators of RKIP/PEBP1 and its binding partners in the context of prostate cancer." (PMID 30115852, 2018). "To explore the last possibility, we queried the cRegulome database to identify transcription factors and microRNAs that target the RKIP/PEBP1 gene and one or more of EMT and autophagy genes in prostate cancer (preparing for publication)." (PMID 30115852, 2018). "RKIP/PEBP1 interacts with EMT and autophagy-related gene products as part of the same functional unit in developing prostate cancer." (PMID 30115852, 2018). "Using the weighted-gene co-expression network analysis of a public-access gene expression dataset, we found that RKIP/PEBP1, an anti-tumor protein, potentially interacts with several key gene products in the autophagy and EMT gene sets during the development of prostate cancer." (PMID 30115852, 2018).
melanoma (30 papers, 2007 to 2025). A malignant, usually aggressive tumor composed of atypical, neoplastic melanocytes. "The RIPK4 and PEBP1 protein in melanoma cell lines were compared to the levels in normal melanocytes." (PMID 36765875, 2023). "The results obtained in the present study confirm the significantly lower expression level of the PEBP1 protein in melanoma cells compared to melanocytes." (PMID 36765875, 2023). "In cancer, PEBP1 expression seems mostly favorable to survival and, for melanoma, an inverse correlation between PEBP1 expression and metastases has been reported." (PMID 28978044, 2017). "PEBP1 and STK11 transcript levels were associated with immunosuppressive properties and responses to immune checkpoint blockade (ICB) therapies, such as anti-PD1 and anti-CTLA4, particularly in melanoma, kidney, and lung cancers." (PMID 40806276, 2025). "PEBP1 levels decrease dramatically with the progression of melanoma." (PMID 36765875, 2023). "Our results suggest that PEBP1 may affect the prognosis of melanoma by LncRNA." (PMID 36313708, 2022). "Since PEBP1 acts as a tumor suppressor in melanoma, we investigated a correlation between the levels of RIPK4 and PEBP1 protein levels in melanoma." (PMID 36765875, 2023). "We observed expressions of ferroptosis related proteins including ALOX5, PEBP1, ACSL4 and ZEB1 in melanoma, which showed a strong cytoplasmic staining." (PMID 36313708, 2022). "The phosphorylation of phosphatidylethanolamine binding protein 1 (PEBP1)—a suppressor of the BRAF/MEK/ERK pathway—via RIPK4 observed in pancreatic cancer did not occur in melanoma." (PMID 36765875, 2023). "It confirms that RIPK4 does not affect the PEBP1/RIPK4 axis or the BRAF/MEK/ERK pathway in melanoma." (PMID 36765875, 2023).
gastric cancer (27 papers, 2011 to 2025). A primary or metastatic malignant neoplasm involving the stomach. "For example, circMTO1 was found to inhibit the initiation and development of gastric carcinoma by increasing the expression of Phosphatidylethanolamine-binding protein 1 (PEBP1) via sponging of miR-3200-5p." (PMID 34277605, 2021). "As for gastric cancer, previous studies exhibit that circ‐MTO1 suppresses its development and progression by regulating microRNA (miR)‐3200‐5p/phosphatidylethanolamine binding protein 1 (PEBP1) axis and miR‐199a‐3p/pro‐apoptotic WT1 regulator (PAWR) axis." (PMID 35478417, 2022).
lung carcinoma (24 papers, 2011 to 2025). "In non-small cell lung cancer (NSCLC), PEBP1 has been proven to be one of the key proteins regulating the proliferation and metastasis of lung cancer cells." (PMID 37622116, 2023). "In NSCLC, the expression level of PEBP1 is closely related to the severity of lung cancer and patients’ prognosis." (PMID 37622116, 2023). "Overexpression of PEBP1 can significantly inhibit the proliferation, migration and invasion of lung cancer, reduce tumor size, and the probability of distant metastasis." (PMID 37622116, 2023). "Accordingly, the results of our analysis show that YY1 is considerably upregulated in HNSC, breast, bladder, and lung cancers (LUSC and LUAD), while PEBP1 is significantly downregulated in all kidney and lung cancer subtypes, as well as in LIHC, HNSC, and STAD." (PMID 37894300, 2023). "We initially investigated pan-cancer the expression of YY1 and PEBP1, and found higher YY1 mRNA levels in HNSC, lung cancer (both LUAD and LUSC), ESCA, BRCA, and BLCA, compared to their corresponding normal tissues." (PMID 37894300, 2023). "In this study, we also report significant differences between high and low YY1 expression in different subtypes of BRCA, KIRC, LUAD, LUSC, and STAD, as well as between high and low PEBP1 expression in different subtypes of KIRC and lung cancers." (PMID 37894300, 2023).
hepatocellular carcinoma (20 papers, 2012 to 2025). A malignant tumor that arises from hepatocytes. "In hepatocellular carcinoma, the down-regulation of PEBP1 resulted in aggressive tumor behavior and poor prognosis." (PMID 37762371, 2023). "One study reported that DHA upregulated the PEBP1 expression by inhibiting its ubiquitination degradation, thus promoting the formation of PEBP1/15-LO (lipoxygenase) and cell membrane lipid peroxidation, finally inducing ferroptosis of hepatocellular carcinoma." (PMID 39021832, 2024). "Lastly, resting mast cells demonstrated a strong positive correlation with PEBP1/STK11 co-expression of in multiple cancers, including hepatocellular carcinoma (LIHC), KICH, KIRC, BRCA, PRAD, LUAD, MESO, THCA, and SARC." (PMID 40806276, 2025).
clear cell renal cell carcinoma (15 papers, 2014 to 2025). "Additionally, YBX1 reads m5C PEBP1 (Phosphatidylethanolamine Binding Protein 1) mRNA in clear cell renal cell carcinoma and 5mC keratin 13 mRNA in gynecologic cancers, preventing their decay, which contributes to tumor progression." (PMID 38255791, 2024). "While reduced levels of urine RKIP appear to reflect its downregulation in clear cell renal cancer, a trend of increased PEBP1 in the CSF of Alzheimer’s patients compared to controls was observed, although its role remains unclear." (PMID 39407890, 2024). "The PEBP1 protein's ubiquitination and degradation can activate the ERK signalling pathway, promoting clear cell renal cell carcinoma progression." (PMID 40591061, 2025). "Meanwhile, circPOLR2A interacts with UBE3C and PEBP1 proteins and promotes the UBE3C-mediated PEBP1 ubiquitination, thereby activating the ERK signaling pathway and facilitating clear cell renal cell carcinoma progression." (PMID 36895010, 2023).
lung adenocarcinoma (14 papers, 2014 to 2025). A carcinoma that arises from the lung and is characterized by the presence of malignant glandular epithelial cells. "On the other hand, PEBP1, FLT3 and IL33 were adversely associated with the outcomes of lung adenocarcinoma patients." (PMID 39311766, 2024). "Consistently, a very recent study also suggested that increased expression of PEBP1 is related to survival status in lung adenocarcinoma patients." (PMID 35222395, 2022).
glioma (13 papers, 2012 to 2024). A benign or malignant brain and spinal cord tumor that arises from glial cells (astrocytes, oligodendrocytes, ependymal cells). "The TRPV2 interactome showed a high association with early glia-related neoplasms, especially glioma/glioblastoma, being ABR, FGF1, KCNJ10, PEBP1, PLP1, SDC3, and TRPV2, the genes associated to these brain neoplasms." (PMID 29719613, 2018). "Down-regulation of PEBP1, also known as the Raf-1 kinase inhibitor protein (RKIP), is associated with glioma progression, and it has been demonstrated that RKIP, by inhibiting MMP-2 and MMP-9 expression, markedly reduces the ability of glioma cells to migrate and invade." (PMID 30845786, 2019). "Phosphatidylethanolamine-binding protein 1 (PEBP1) and Hsp70-binding protein 1 (HSPBP1) were reduced in glioma versus normal brain tissues." (PMID 37762371, 2023). "Decreased levels of PEBP1 were observed in high-grade gliomas compared to the non-neoplastic tissues and lower-grade gliomas." (PMID 37762371, 2023). "Interestingly, phosphatidylethanolamine-binding protein 1 (PEBP1), also known as raf kinase protein inhibitor (RKIP), was decreased in high grade gliomas in relation to the non-neoplastic tissue and lower grade gliomas, as previously demonstrated by our group." (PMID 26108672, 2015).
pancreatic cancer (13 papers, 2011 to 2025). "RIPK4 was shown to activate the CRAF-MEK-ERK pathway by promoting the degradation of proteasome-mediated phosphatidylethanolamine binding protein 1 (PEBP1) in pancreatic cancer." (PMID 38111008, 2023). "RIPK4 activates the RAS/RAF/MEK/ERK pathway in pancreatic cancer by promoting the degradation of phosphatidylethanolamine binding protein 1 (PEBP1)." (PMID 36765875, 2023). "In contrast, RIPK4 facilitated pancreatic cancer cell migration and invasion via the phosphatidylethanolamine binding protein 1 (PEBP1) degradation-induced activation of the RAF1/MEK/ERK pathway." (PMID 35186499, 2022). "Activation of the RAF1/MEK/ERK pathway is induced by PEBP1 degradation in pancreatic cancer and promotes the migration and invasion of pancreatic cancer cells." (PMID 34222329, 2021). "Downregulation of PEBP1 has been observed in liver and pancreatic cancer, where it may contribute to aggressive tumor behavior and poor prognosis." (PMID 37985807, 2023). "In pancreatic cancer, RIPK4 can promote cell migration and invasion via the phosphatidylethanolamine binding protein 1 (PEBP1) degradation-induce activation of the RAF1/MEK/ERK signaling pathway." (PMID 35186499, 2022).
Alzheimer disease (12 papers, 2009 to 2024). A progressive, neurodegenerative disease characterized by loss of function and death of nerve cells in several areas of the brain leading to loss of cognitive function such as memory and language. "Human Phosphatidylethanolamine binding protein 1 (hPEBP1) also known as Raf kinase inhibitory protein (RKIP), affects various cellular processes, and is implicated in metastasis formation and Alzheimer's disease." (PMID 22558375, 2012). "In a mouse model of Alzheimer's disease the loss of PEBP1 function was observed and behavioral tests revealed a learning deficit." (PMID 19405953, 2009). "PEBP1 affects various diseases including cancer, Alzheimer’s disease, and pancreatitis, which makes it a logical target for individualized therapy and disease-specific intervention." (PMID 34073365, 2021). "PEBP1 (also known as Raf1 kinase inhibitory protein [RKIP]) belongs to the family of PE-binding proteins (PEBPs) and has been implicated in various diseases, including cancer, Alzheimer’s disease, diabetes, and retinopathies." (PMID 39531326, 2024). "In addition, PEBP1 expression was shown to be decreased in various neurological disorders such as stroke, mild cognitive impairments, and Alzheimer’s disease." (PMID 31683736, 2019). "Besides, the disruption of PEBP1 has been reported to be related with a diverse range of diseases, namely, pancreatitis, cancer and Alzheimer’s disease, making it a potential target for disease therapy." (PMID 27436115, 2016).